AKR1D1 (aldo-keto reductase family 1 member D1)
Description:
Catalyzes the stereospecific NADPH-dependent reduction of the C4-C5 double bond of bile acid intermediates and steroid hormones carrying a delta(4)-3-one structure to yield an A/B cis-ring junction. This cis-configuration is crucial for bile acid biosynthesis and plays important roles in steroid metabolism. Capable of reducing a broad range of delta-(4)-3-ketosteroids from C18 (such as, 17beta-hydroxyestr-4-en-3-one) to C27 (such as, 7alpha-hydroxycholest-4-en-3-one).
Synonyms: SRD5B1; 3o5bred; CBAS2
Tractability: Small molecule: a structure with a bound ligand is known; it has a high-quality binding pocket. PROTAC: ubiquitination databases record sites on it; its protein half-life has been measured.
Target class: Enzyme; Oxidoreductase
Gene: Protein-coding gene on chromosome 7 (138,002,324 to 138,118,306, forward strand). Ensembl gene ENSG00000122787.
Subcellular location: Cytoplasm
Subcellular location (Human Protein Atlas): Nucleoplasm; Cytosol
Pathways (Reactome):
Metabolism: Synthesis of bile acids and bile salts via 24-hydroxycholesterol; Synthesis of bile acids and bile salts via 27-hydroxycholesterol; Synthesis of bile acids and bile salts via 7alpha-hydroxycholesterol
Gene Ontology:
Molecular function: protein binding; alcohol dehydrogenase (NADP+) activity; aldose reductase (NADPH) activity; ketosteroid monooxygenase activity; steroid binding; steroid dehydrogenase activity; 17-beta-hydroxysteroid dehydrogenase (NADP+) activity; Delta4-3-oxosteroid 5beta-reductase activity; oxidoreductase activity
Biological process: androgen metabolic process; bile acid biosynthetic process; C21-steroid hormone metabolic process; cholesterol catabolic process; digestion; hormone metabolic process; monocarboxylic acid metabolic process; steroid metabolic process
Cellular component: cytoplasm; cytosol
Genetic constraint (gnomAD): Loss-of-function variants: 28 observed, 33.19 expected, observed/expected ratio (o/e) 0.84, 90% interval 0.62 to 1.16. The upper end of that interval is the gene's LOEUF score, 1.16, which puts it in group 5 of 6, group 1 being the genes least tolerant of losing a copy. Missense variants: 333 observed, 386.48 expected, observed/expected ratio (o/e) 0.86, 90% interval 0.79 to 0.94. Synonymous variants: 118 observed, 134.3 expected, observed/expected ratio (o/e) 0.88, 90% interval 0.76 to 1.02.
Gene-disease validity (ClinGen):
ClinGen rates the evidence that AKR1D1 causes each of these diseases.
congenital bile acid synthesis defect 2 (autosomal recessive): Definitive.
Homologues: Orthologues: chimpanzee AKR1D1 (100% identical), macaque AKR1D1 (99% identical), pig AKR1D1 (90% identical), mouse Akr1d1 (82% identical), rat Akr1d1 (82% identical), guinea pig AKR1D1 (80% identical), Caenorhabditis elegans Y39G8B.1 (40% identical), Caenorhabditis elegans Y39G8B.2 (32% identical), Caenorhabditis elegans F53F1.3 (29% identical), Caenorhabditis elegans F53F1.2 (28% identical), Caenorhabditis elegans C01G5.5 (27% identical), Drosophila melanogaster CG18547 (15% identical), and 2 more. Paralogues in human: AKR1C1 (58% identical), AKR1C2 (57% identical), AKR1C4 (56% identical), AKR1C8 (56% identical), AKR1C3 (56% identical), AKR1B10 (50% identical), AKR1B1 (49% identical), AKR1B15 (47% identical), AKR1E2 (44% identical), AKR1A1 (44% identical), AKR7A2 (25% identical), AKR7L (24% identical), and 4 more.
Diseases named in the same sentence as AKR1D1 in open-access papers:
AKR1D1 is named in the same sentence as 43 diseases in open-access papers, as found by Europe PMC text mining. Sharing a sentence is not in itself a finding about the gene and the disease. The quoted sentences say what the papers report.
hepatoma (10 papers, 2017 to 2025). "Expression of AKR1D1 variants were measured in human liver biopsies and hepatoma cell lines by qPCR." (PMID 33502336, 2021). "In order to investigate the role of AKR1D1 within the human liver in vitro, the expression pattern of AKR1D1 expression was explored in four different human hepatoma cell lines, using qPCR." (PMID 31330134, 2019). "Genetic manipulation of AKR1D1 regulates the metabolic phenotype of human hepatoma cell lines, driving steatosis and inflammation." (PMID 31330134, 2019). "Consistent with our previous study, AKR1D1 is able to regulate glucocorticoid availability in human hepatoma cells, revealing the presence of an additional pathway for intracellular steroid hormone metabolism within human liver." (PMID 31330134, 2019). "In this work, genetic manipulation of AKR1D1 expression and activity regulated the inflammatory response in human hepatoma cells by enhancing the expression and secretion of pro-inflammatory cytokines alongside activation of the NF-κB pathway." (PMID 31330134, 2019). "Our in vitro experiments have shown that limiting AKR1D1 expression and activity regulates fundamental metabolic processes within human hepatoma cells that govern hepatic insulin sensitivity, lipid accumulation and carbohydrate metabolism." (PMID 31330134, 2019). "We found that CDCA markedly repressed AKR1D1 expression in vitro in human hepatoma HepG2 cells and in vivo in mice." (PMID 28125709, 2017). "In vitro studies using human hepatoma cells have linked negative expression of AKR1D1 to Nonalcoholic fatty liver disease (NAFLD)." (PMID 39021677, 2024). "Mice generate 5β-reduced glucocorticoid metabolites, and AKR1D1 controls glucocorticoid availability and action in human hepatoma cell lines; nevertheless, circulating corticosterone levels were normal in Akr1d1–/– mice and hepatic expression of glucocorticoid-regulated genes was unchanged." (PMID 35318963, 2022). "Also, AKR1D1 over-expression decreased glucocorticoid production and glucocorticoid receptor activation in human hepatoma cells." (PMID 33493134, 2021). "Therefore, our study suggested that AKR1C3 and AKR1D1 might be candidates for hepatocellular carcinoma targeted therapy." (PMID 33493134, 2021). "Following over-expression of AKR1D1 in HepG2 and HEK293 cells, cortisone clearance and 5β-THE generation were increased, providing additional evidence for the potent ability of AKR1D1 to regulate steroid hormone availability within human hepatoma cells." (PMID 31330134, 2019).
cholestasis (6 papers, 2013 to 2025). Impairment of the bile flow caused by obstruction within the liver, or outside the liver in the bile duct system. "The biochemical studies support the association of the AKR1D1 mutants with cholestasis/liver failure and bile acid metabolism deficiency." (PMID 36768194, 2023). "Δ4-3-Oxosteroid 5β-reductase (AKR1D1) deficiency typically causes severe cholestasis occurs in newborns, leading to death unless patients are treated with primary bile acids." (PMID 38034430, 2023). "How this patient with AKR1D1 mutation avoided severe cholestasis during and after UDCA monotherapy is unclear." (PMID 38034430, 2023). "In line with this, a significant number of studies have linked cholestasis and consequent liver inflammation and dysfunction with mutations in AKR1D1." (PMID 31330134, 2019). "In addition, we studied 3 Vietnamese siblings who shared a AKR1D1 mutation, including a 2-year-old boy with cholestasis since birth who is undergoing primary bile acid therapy with chenodeoxycholic acid (CDCA)." (PMID 38034430, 2023). "Thus, AKR1D1 deficiency may have 2 different manifestations, such as fatal infantile progressive cholestasis or an adult-onset neurologic disorder." (PMID 38034430, 2023). "We also have been following other healthy patients with AKR1D1 mutation who have never developed cholestasis and have not been treated." (PMID 38034430, 2023). "However, we encountered an AKR1D1 deficiency patient treated with only ursodeoxycholic acid who had cholestasis until about 1 year of age but then grew up healthy without further treatment." (PMID 38034430, 2023).
Cirrhosis (3 papers, 2021 to 2025). A chronic disorder of the liver in which liver tissue becomes scarred and is partially replaced by regenerative nodules and fibrotic tissue resulting in loss of liver function. "In AKR1D1 deficiency, 3-oxo-Δ4 bile acids typically accumulate in hepatocytes during the neonatal period and early infancy, leading to chronic cholestasis and consequent cirrhosis." (PMID 38034430, 2023). "Alternatively, as is the case with the inborn error of metabolism with genetically impaired Δ4-3-oxosteroid 5β-reductase deficiency, AKR1D1 activity may be impaired by an as yet undefined mechanism, leading to worsening cirrhosis." (PMID 33859329, 2021). "It is therefore probable that the metabolic activity of AKR1D1 declines with increasing severity of cirrhosis in a manner that is unaffected by the presence of hepatic tumors." (PMID 33859329, 2021). "This would have permitted us to confirm the role of AKR1D1 in fetal bile acid disposition, which we posited is compromised with increasing severity of cirrhosis." (PMID 33859329, 2021). "Untreated infants with AKR1D1 deficiency usually show rapid progression to cirrhosis unless in the absence of prompt clinical intervention." (PMID 38034430, 2023). "Additionally, the top 5 biological functional hub genes in NAFLD vs. control (CXCL9, NOS2, SERPINE1, FABP4, and LPL) and NAFLD vs. cirrhosis (AKR1D1, UGT2B17, CYP26B1, LIPC, and DGAT2) groups were identified through PPI analysis among lipid, immune, and metabolism dysregulated genes." (PMID 40365443, 2025). "Among all, the top 5 hub genes identified for NAFLD vs. control were CXCL9, NOS2, SERPINE1, FABP4, and LPL, whereas AKR1D1, UGT2B17, CYP26B1, LIPC, and DGAT2 were identified as the top 5 hub genes for the NAFLD vs. cirrhosis group." (PMID 40365443, 2025).
liver disease (3 papers, 2013 to 2025). "Major questions persist about what determinants and mechanisms result in liver disease or its absence in the presence of AKR1D1 mutations." (PMID 38034430, 2023). "According to Clayton, the same mutation in AKR1D1 in the same family can result in phenotypes ranging from death in infancy from liver failure to the absence of clinical liver disease in the fourth decade." (PMID 38034430, 2023).
non-alcoholic fatty liver disease (3 papers, 2019 to 2022). "Previous studies showed that the dysregulation of AKR1D1 might lead to non-alcoholic fatty liver disease (NAFLD) and NAFLD was the most common reason for chronic liver disease in Western countries." (PMID 33493134, 2021).
Obesity (3 papers, 2019 to 2022). Accumulation of substantial excess body fat. "Male Akr1d1–/– mice were not protected against diet-induced obesity and insulin resistance." (PMID 35318963, 2022).
steatosis (3 papers, 2019 to 2024). Increased lipid within the cytoplasm of cells. "The AKR1D1 hub gene, which has been identified in association with AST, is associated with steatosis and inflammation and regulates key metabolic processes." (PMID 39021677, 2024). "In human liver biopsies taken from 34 obese patients, AKR1D1 mRNA expression was reported to decrease with advancing steatosis, fibrosis and inflammation." (PMID 33859329, 2021). "It has been reported that AKR1D1 hepatic expression in adults decreased with progression of steatosis, fibrosis and inflammation and in type 2 diabetic patients." (PMID 33859329, 2021). "In human liver biopsies, AKR1D1 expression decreased with advancing steatosis, fibrosis and inflammation." (PMID 31330134, 2019).
endometriosis (2 papers, 2022 to 2023). The growth of functional endometrial tissue in anatomic sites outside the uterine body. "Moreover, a clinical phase II trial for an endometriosis drug was stopped due to hepatotoxicity that was probably caused by inhibition of AKR1D1, important in bile acid metabolism." (PMID 35208174, 2022). "The results showed that SNP sites such as AKR1C2 (rs116900756), AKR1D1 (rs9642092), CYP11B1 (rs1134095), CYP3A7 (rs45446698) appeared simultaneously in the MR analysis results of TT and BioT on ovarian cancer, endometrial cancer, endometriosis, PCOS and POF." (PMID 38075074, 2023).
Insulin resistance (2 papers, 2021 to 2022). Increased resistance towards insulin, that is, diminished effectiveness of insulin in reducing blood glucose levels. "Male Akr1d1–/– mice were partially protected against diet-induced hypertriglyceridemia but not glucose intolerance or insulin resistance." (PMID 35318963, 2022).
congenital bile acid synthesis defect (1 paper, 2022). "Congenital bile acid synthesis defect (BASD) type 2 is a rare autosomal recessive inherited disease caused by a defect in the aldo-keto reductase family 1 member D1 (AKR1D1) gene." (PMID 35758383, 2022).
depression (1 paper, 2025). "Following the analysis of the metabolic pathways, seven genes including ALOX5, LTA4H, CYP4Y, PLA2G2C, AKR1C1, AKR1D1 and CYP17A1 were employed to elucidate further the potential mechanisms underlying CS treatment of depression." (PMID 40370520, 2025).
gallstones (1 paper, 2023). Solid crystalline precipitates in the biliary tract, usually formed in the gallbladder, resulting in the condition of cholelithiasis. "The downregulation of AKR1C4 and AKR1D1, which are involved in the synthesis of bile acids and bile salts that enhance cholesterol solubility, may promote gallstone formation." (PMID 38111640, 2023).
Hepatic fibrosis (1 paper, 2023). The presence of excessive fibrous connective tissue in the liver. "The expression of Cyp7a1 and Akr1d1 was not significantly downregulated in rats with hepatic fibrosis, but this trend was significantly reversed after the transplantation of ADMSCs." (PMID 38003277, 2023).
hyperlipidemia (1 paper, 2022). "It is therefore possible that loss of hepatic FXR and TGR5 signalling in Akr1d1–/– males could increase VLDL synthesis and reduce fatty acid uptake, simultaneously reducing hepatic triacylglycerol levels and contributing to hyperlipidemia." (PMID 35318963, 2022).
hypertriglyceridemia (1 paper, 2022). A laboratory test result indicating elevated triglyceride concentration in the blood. "Hypertriglyceridemia is commonly associated with increased intramyocellular triacylglycerol accumulation, and skeletal muscle triacylglycerol levels were increased in the Akr1d1–/– males." (PMID 35318963, 2022). "Male Akr1d1–/– mice exhibit lipodystrophy with reduced lipid accumulation in adipose and liver as well as hypertriglyceridemia and high serum free fatty acids." (PMID 35318963, 2022). "Despite hypertriglyceridemia and reduced adipose mass, there was no change in the expression of key lipid metabolism genes in the gonadal fat from Akr1d1–/– males, and IPA (causal network) did not predict altered lipid accumulation." (PMID 35318963, 2022). "At 30 weeks of age, male, but not female, Akr1d1–/– mice were more insulin tolerant and had reduced lipid accumulation in the liver and adipose tissue yet had hypertriglyceridemia and increased intramuscular triacylglycerol." (PMID 35318963, 2022).
liver cancer (1 paper, 2020). An epithelial or non-epithelial malignant neoplasm that arises from the liver. "At the cellular level, YBX3 and CH25H were highly expressed in liver cancer cell lines, and ABCA6, PLIN5, AMACR, AKR1D1, CYP27A1, CYP46A1 were highly expressed in liver cancer cell lines in CCLE." (PMID 32627826, 2020).
liver dysfunction (1 paper, 2023). "However, 3 of the 5 patients with an AKR1D1 gene mutation in this case series had no liver dysfunction." (PMID 38034430, 2023).
ovarian tumor (1 paper, 2025). "There was evidence indicating that the decrease of AKR1C1 and AKR1D1 played an important role in the formation of ovarian tumor tissues and inflammation." (PMID 40370520, 2025).
small cell lung carcinoma (1 paper, 2022). Small cell lung cancer (SCLC) is a highly aggressive malignant neoplasm, accounting for 10-15% of lung cancer cases, characterized byrapid growth, and early metastasis.
cancer (5 papers, 2016 to 2023). A tumor composed of atypical neoplastic, often pleomorphic cells that invade other tissues. "AKR1C3 plays crucial roles in multiple cancers, and a low expression level of AKR1D1 predicted poor prognosis and short median survival time." (PMID 34104649, 2021). "Moreover, molecular modeling studies using PyRx revealed that 4a, among all SOXs, was found to be the best inhibitor of distinct biomarkers associated with cancer progression, i.e., human CD-44, EGFR, AKR1D1, and HER-2." (PMID 37108498, 2023). "Synthesized SOXs (4a–h) were further subjected to the drug-likeness, ADME, and in silico screening for their inhibitory efficacy against cancer-specific molecular markers, i.e., CD44, AKR1D1, HER-2, and EGFR." (PMID 37108498, 2023). "Overall, our results suggest that SOX (4a) targets CD-44, EGFR, AKR1D1, and HER-2 and induces ROS generation in cancer cells." (PMID 37108498, 2023).
tumor (4 papers, 2014 to 2025). "And the expression of AKR1D1 was downregulated in tumor tissue." (PMID 33493134, 2021). "Furthermore, 2.8% of tumor samples showed AKR1C3 mutations, including amplifications, deep deletions, and missense mutations; 2% of the samples also showed genetic alterations in the AKR1D1 gene." (PMID 33493134, 2021). "In tumor tissue, AKR1C3 and AKR1D1 were secreted by HCC cells." (PMID 33493134, 2021). "No significant changes in expression of AKR1B1, AKR1D1, AKR7A2, CBR1, CYP2C8, and CYP2C9 between tumor and control tissues were found." (PMID 25526449, 2014).
metabolic disease (3 papers, 2019 to 2022). A congenital disorder (due to inherited enzyme abnormality) or acquired (due to failure of a metabolically important organ) disorder resulting from an abnormal metabolic process. "Aberrant expression of AKR1D1 contributes to BA synthesis defect, metabolic disorders and liver failure." (PMID 36572736, 2022).
AKR1D1 also shares sentences with these, for which no sentence is quoted: type 2 diabetes (4 papers); liver failure (3); Hepatic steatosis (2); liver cirrhosis (2); Aagenaes syndrome (1); Alagille syndrome (1); cerebrotendinous xanthomatosis (1); Cholestatic liver disease (1); Dubin-Johnson syndrome (1); endometrial cancer (1); Glucose intolerance (1); GRACILE syndrome (1); Jaundice (1); lipodystrophy (1); lymphedema (1); myofibromatosis (1); non-alcoholic steatohepatitis (1); ovarian carcinoma (1); schizophrenia (1); squamous cell carcinoma (1); Zellweger spectrum disorders (1).